PANK3 (pantothenate kinase 3)
Description:
Catalyzes the phosphorylation of pantothenate to generate 4'-phosphopantothenate in the first and rate-determining step of coenzyme A (CoA) synthesis.
Synonyms: FLJ12899
Tractability: Small molecule: a structure with a bound ligand is known; a high-quality ligand is known; it has a high-quality binding pocket. PROTAC: ubiquitination databases record sites on it; a small molecule that binds it is known.
Target class: Enzyme; Transferase
Chemical probes: PZ2891 (high quality)
Gene: Protein-coding gene on chromosome 5 (168,548,495 to 168,579,600, reverse strand). Ensembl gene ENSG00000120137.
Subcellular location: Cytoplasm
Subcellular location (Human Protein Atlas): Golgi apparatus
Pathways (Reactome):
Metabolism: Coenzyme A biosynthesis
Gene Ontology:
Molecular function: acetyl-CoA binding; ATP binding; pantothenate kinase activity; protein homodimerization activity; vitamin binding
Biological process: coenzyme A biosynthetic process; phosphorylation
Cellular component: cytoplasm; cytosol; nucleus
Genetic constraint (gnomAD): Loss-of-function variants: 15 observed, 30.65 expected, observed/expected ratio (o/e) 0.49, 90% interval 0.33 to 0.75. The upper end of that interval is the gene's LOEUF score, 0.75, which puts it in group 3 of 6, group 1 being the genes least tolerant of losing a copy. Missense variants: 234 observed, 378.97 expected, observed/expected ratio (o/e) 0.62, 90% interval 0.55 to 0.69. Synonymous variants: 124 observed, 143.01 expected, observed/expected ratio (o/e) 0.87, 90% interval 0.75 to 1.01.
Homologues: Orthologues: chimpanzee PANK3 (100% identical), macaque PANK3 (100% identical), pig PANK3 (99% identical), guinea pig PANK3 (99% identical), mouse Pank3 (99% identical), rat Pank3 (99% identical), rabbit PANK3 (97% identical), dog PANK3 (96% identical), tropical clawed frog pank3 (91% identical), Drosophila melanogaster fbl (62% identical). Paralogues in human: PANK2 (82% identical), PANK1 (79% identical), PANK4 (36% identical).
Diseases named in the same sentence as PANK3 in open-access papers:
PANK3 is named in the same sentence as 9 diseases in open-access papers, as found by Europe PMC text mining. Sharing a sentence is not in itself a finding about the gene and the disease. The quoted sentences say what the papers report.
breast carcinoma (2 papers, 2012 to 2018). "Moreover, pantothenate kinase 3 (PANK3) and Coenzyme A synthase (COASY) are known breast cancer genes." (PMID 23281707, 2012).
melanoma (1 paper, 2022). A malignant, usually aggressive tumor composed of atypical, neoplastic melanocytes. "Further analysis confirmed that miR-107 and its host gene PANK1, but not another gene of the PANK family (PANK3) were downregulated in human and murine melanoma cell lines." (PMID 36612285, 2022).
renal carcinoma (1 paper, 2025). A carcinoma arising from the epithelium of the renal parenchyma or the renal pelvis. "Furthermore, exosomal miR-222-3p derived from renal cancer cells is shown to induce the transformation of fibroblasts into CAFs by down-regulating the target gene PANK3 and inducing metabolic reprogramming." (PMID 40280913, 2025). "Furthermore, the down-regulation of PANK3 induced by exosomes derived from renal cancer cells was identified as a crucial step in fibroblast activation." (PMID 40280913, 2025).
seminoma (1 paper, 2025). A radiosensitive malignant germ cell tumor found in the testis (especially undescended), and extragonadal sites (anterior mediastinum and pineal gland). "The Human Protein Atlas (proteinatlas.org) indicates that higher PANK3 protein abundance is associated with seminoma subtypes but has lower abundance in non-seminomas (proteinatlas.org/ENSG00000120137-PANK3/cancer/testis + cancer#IHC)." (PMID 39809819, 2025).
cancer (2 papers, 2022 to 2025). A tumor composed of atypical neoplastic, often pleomorphic cells that invade other tissues. "We found that separating the cytosolic proteins by sub-cellular fractionation significantly reduced the non-specific signals and allowed reliable detection of endogenous PANK3 proteins in a broad range of cancer cell lines." (PMID 36139163, 2022). "The CRISPR experiment also evidenced that PANK3 is a dispensable gene in most cancer cells, which is consistent with large-scale CRISPR and RNAi screen (DepMap) as well as mouse germline KO studies." (PMID 36139163, 2022). "Sub-cellular fractionation shows that PANK3 is overwhelmingly cytosolic and expressed broadly across cancer cell lines." (PMID 36139163, 2022). "We demonstrate that MDA-299-62A can reliably detect purified recombinant human PANK3 and endogenous PANK3 protein in cancer cell lysates, with the band specificity validated by PANK3 CRISPR knockout cancer cell lines." (PMID 36139163, 2022). "We also performed knockdown studies using a doxycycline-inducible system and found that MDA-299-62A can reliably detect shRNA-mediated knockdown of PANK3 in cancer cells." (PMID 36139163, 2022). "Additionally, we also independently generated PANK1, PANK2, or PANK3 knockout clones in multiple different cancer cell lines to validate the band specificity and serve as a negative control for the antibodies." (PMID 36139163, 2022). "Our investigations of PANK proteins as potential precision oncology collateral lethality targets (PANK1 is co-deleted as part of the PTEN locus in some highly aggressive cancers) were severely hindered by a dearth of commercial antibodies that can reliably detect endogenous PANK3 protein." (PMID 36139163, 2022). "We demonstrate that a clone (Clone MDA-299-62A) can reliably detect endogenous PANK3 protein in cancer cell lines, with band-specificity confirmed by CRISPR PANK3 knockout and knockdown cell lines." (PMID 36139163, 2022). "To conclusively validate that the antibody was indeed recognizing the endogenous PANK3 protein, we employed the CRISPR–Cas9 technology to knock out PANK3 protein in two different cancer cell lines—HAP1 and HeLa." (PMID 36139163, 2022).
hematopoietic system tumors (1 paper, 2025). "Previous research has identified that a high expression of the PANK3 gene serves as a biomarker for a favorable prognosis in hematopoietic system tumors." (PMID 40280913, 2025).
tumor (1 paper, 2025). "Overall, these findings suggest that tumor-derived exosomal miR-222-3p directly targets PANK3 and regulates fibroblast activation." (PMID 40280913, 2025). "In conclusion, our findings demonstrate that tumor-derived exosomal miR-222-3p induces aerobic glycolysis and prompts fibroblast activation into CAFs by downregulating PANK3." (PMID 40280913, 2025).
PANK3 also shares sentences with these, for which no sentence is quoted: atherosclerosis (1 paper); testis (1).